INS (insulin)
Diseases named in the same sentence as INS in open-access papers (continued):
Sharing a sentence is not in itself a finding about the gene and the disease.
diabetes (continued). "Another study has shown that thrice daily biphasic human insulin regimen is non-inferior to the basal- bolus insulin analogue regimen in terms of efficacy and safety in patients with poorly controlled type 2 diabetes mellitus." (PMID 32448382, 2020). "The severity of periodontitis was elevated in the individuals with treatment-naïve diabetes in comparison to nondiabetic people, and treatment with metformin, insulin or some other hypoglycemic drugs did not alleviate the severity of periodontitis." (PMID 32634783, 2020). "It is important that practical guidance/recommendations relevant to the treatment landscape in Australia, where insulin degludec is not available, are accessible to diabetes care providers." (PMID 32290465, 2020). "This condition is caused either by pancreatic disorders resulting in low insulin levels (type 1 diabetes mellitus, T1DM) or insulin-resistant cells that do not respond properly to insulin (type 2 diabetes mellitus, T2DM)." (PMID 33120934, 2020). "Diabetes is a disease that occurs when sugar levels in the blood can no longer be controlled by a hormone called insulin." (PMID 33164744, 2020). "Diabetes mellitus (DM) is a chronic metabolic disease characterized by high levels of blood glucose due to a lack of insulin secretion or insulin resistance." (PMID 31991895, 2020). "Recent evidence from experimental models of diabetes suggests that urocortin 2 and 3 (UCN2–3) might be involved in the regulation of insulin secretion and blood glucose levels." (PMID 32244319, 2020). "The remaining persons had insulin-dependent (18.8%) or non-insulin-dependent (7.8%) type 2 diabetes mellitus or other forms of diabetes mellitus, such as gestational diabetes (3.1%)." (PMID 33050656, 2020). "Men with T2DM and prediabetes also have higher blood insulin levels than men without diabetes, but the differences were statistically insignificant." (PMID 32733043, 2020). "Patient 2 is a 45-year-old man treated with high insulin doses (100 UI/day) for diabetes mellitus diagnosed at 34, complicated with non-proliferative retinopathy and microalbuminuria." (PMID 32012908, 2020). "Participants were divided into four diabetes medication categories: oral diabetes medication only, insulin only, both oral diabetes medication and insulin and no to both oral diabetes medication and insulin." (PMID 32802365, 2020). "A prior study of middle age adults without diabetes showed an inverse relationship between insulin and SDNN, as well as between insulin and RMSSD using 2-min electrocardiography recordings (n = 8971)." (PMID 32393179, 2020). "But in previous versions, at the time when a lot of the patients might have been diagnosed, the descriptor for E11 was “non-insulin dependent diabetes mellitus” and as some patients with T2DM are treated with insulin this descriptor might create confusion." (PMID 32051506, 2020). "Diabetes mellitus is a well-known chronic metabolic disease that poses a long-term threat to human health and is characterized by a relative or absolute lack of insulin, resulting in hyperglycemia." (PMID 33287318, 2020). "The introduction of insulin in 1921 commuted the death sentence to a life sentence but emphasised that self-evident distinction between the insulin-dependent form of diabetes and everything else, then called non-insulin-dependent diabetes, now type 2 diabetes." (PMID 31813006, 2020). "In addition, adipocyte MIF mRNA concentration was also positively associated with adipocytes diameter and independently predicted the peripheral insulin action and the expression of MIF was increased in patients with obesity and diabetes." (PMID 32265835, 2020). "Second, based on our practice, patients with diabetes can get insulin pumps without a prescription from online markets outside the country." (PMID 33334003, 2020). "The diabetes mellitus group showed no statistical difference in glucose tolerance and insulin tolerance compared with exenatide treatment group." (PMID 31199578, 2020).
diabetes (continued). "We did not observe the impact of BMI > 25 kg/m2, smoking, alcohol consumption, duration of diabetes, the type of therapy, i.e., multiple dose injection (MDI) or continuous subcutaneous insulin infusion (CCII), or the use of glucose monitoring systems on the results of the scales." (PMID 32580278, 2020). "In this study, most of the patients were female, were obese, were not meeting the goals for glycaemic control, were not using insulin, had a mean age of 59.43 years and had a mean time since diagnosis with diabetes of 12 years." (PMID 32266011, 2020). "Overall, insulin was used in 82% (n=1,959) of patients, including 95% (n=1,203) with diabetes (n=1,258) and 67% (n=756) without diabetes (n=1,132)." (PMID 33118731, 2020). "Injection site inspection: another issue of note surrounding Algerian diabetes patients ́ injection habits is the follow-up of patients under insulin: 82% do not remember the last time they had their injection site inspected, compared with 39% worldwide." (PMID 33193981, 2020). "Factors like unemployment, lack of family/social support, duration of diabetes of >10 years, poor knowledge of diabetes, taking insulin alone and taking metformin plus glibenclamide were associated significantly with poor glycemic control." (PMID 32528672, 2020). "Type 2 diabetes mellitus (T2DM) is characterized by insulin insensitivity as a result of insulin resistance, declining insulin production, and eventual pancreatic beta-cell failure, which leads to a decrease in glucose transport into the liver, muscle cells, and fat cells." (PMID 33352698, 2020). "In our study, all baseline characteristics including body mass index, comorbidities, family history of diabetes, history of GDM among patients, mean fasting glucose and postprandial blood glucose at the time of diagnosis of GDM in acarbose and insulin group were similar except mean age." (PMID 33403188, 2020). "STZ selectively destroys pancreatic islets, leading to lack of insulin and hyperglycemia, whereas in db/db mice diabetes follows obesity and insulin resistance generated by a recessive mutation in the leptin receptor gene." (PMID 32666590, 2020). "Type 2 diabetes mellitus (T2DM) is a prevalent non-communicable disease characterized by hyperglycemia resulting from the combination of defects in insulin secretion, resistance to insulin action, and excessive glucagon secretion." (PMID 32754118, 2020). "Diabetes mellitus is a chronic disease with either a lack of insulin production or, more commonly, resistance to insulin, leading to hyperglycaemia." (PMID 32992565, 2020). "Type 2 diabetes mellitus (T2DM) is a progressive disease which gradually reduces pancreatic beta-cell function such as insulin secretory capacity and increases insulin resistance in various insulin target tissues." (PMID 32005949, 2020). "Type 2 diabetes mellitus (T2DM) is characterized by increasing insulin resistance concurrent with a not fully compensatory increase in insulin secretion from the pancreatic beta-cells, resulting in pathological hyperglycemia." (PMID 32903679, 2020). "Overall, the incidence of major complications was the highest in patients without diabetes that received insulin." (PMID 33118731, 2020). "At the present time, the use of IV insulin in patients without diabetes remains experimental, but it can be safely administered with close monitoring in situations where lipid apheresis is not preferable." (PMID 33291273, 2020). "For example, there was no disease point person to administer insulin during school or any person responsible for managing diabetes in the school." (PMID 33233468, 2020). "It should be noticed that the culture conditions that we used here with high glucose and high insulin are not directly comparable with in vivo conditions observed in cases of glucose intolerance or diabetes." (PMID 32618419, 2020).
diabetes (continued). "Studies suggest that central arterial stiffness is greater in adults with diabetes and, among adults without diabetes, central arterial stiffness is greater with greater insulin resistance." (PMID 31992297, 2020). "Diabetes mellitus type 2 is the non-insulin-dependent form of diabetes mellitus, and is characterized by impaired function of pancreatic β-cells, resulting in insufficient insulin production, insulin resistance, and an increased plasma glucose level." (PMID 33003543, 2020). "Fasting insulin, glucose, glycosylated hemoglobin (HbA1c), and homeostatic model assessment of insulin resistance (HOMA-IR) were analyzed at baseline and 2 years after surgery for patients with overt type 2 diabetes, prediabetes, or non-diabetes." (PMID 32314253, 2020). "Patients treated with meal plan/physical activity alone (n = 1685, 2.5%) and those who did not use OGLD, insulin or diet for their diabetes (n = 137, 0.2%) were excluded from this analysis." (PMID 31901950, 2020). "Key reasons cited by patients for nonachievement of glycemic targets included lack of insulin titration, fear of hypoglycaemia, and lack of diabetes education." (PMID 32569176, 2020). "During diabetes, HIF signalling is reduced along with the reduction in glycolytic enzymes; therefore, the resultant reduction in metabolic rate reduces ATP production and prevents insulin release from β cells." (PMID 32816039, 2020). "Given that anti-HMGB1 treatment reversed newly diagnosed diabetes, spontaneous diabetic NOD females were treated with sub-therapeutic doses of insulin for at least 4 weeks prior to transplantation, and by then almost no functional beta cells could be detected." (PMID 32072192, 2020). "The traditional treatment for diabetes usually requires frequent insulin injections to maintain normoglycemia, which is painful and difficult to achieve blood glucose control." (PMID 32664978, 2020). "Risk-adjusted clinical outcomes among 2,390 cardiac surgery patients with and without diabetes receiving perioperative insulin." (PMID 33118731, 2020). "In addition, long-acting insulin compared with no insulin may be associated with an increased risk of pancreatic cancer although it may just be an indicator of long-lasting and/or severe diabetes." (PMID 33134820, 2020). "The small number of subjects does not allow us to make conclusions as to the separate effects of diabetes and insulin resistance, as insulin resistance was not measured in this study." (PMID 32344559, 2020). "In forward stepwise regression analyses, insulin clearance was an independent determinant of cIMT in subjects with newly diagnosed diabetes mellitus (r2 = 0.2828; p = 0.0378) and without diabetes mellitus (r2 = 0.4301; p < 0.0001)." (PMID 33384433, 2020). "The pathogenesis of diabetes involves insulin resistance in the peripheral tissues, such as adipose tissue, muscle, and liver, and a lack of insulin secretion from pancreatic β-cells, leading to abnormal glucose metabolism." (PMID 33374137, 2020). "First, in this study, we did not assess the pharmacological treatment of diabetes with metformin or insulin." (PMID 33134820, 2020). "These reinforces the kidney contribution to diabetes development and highlights insulin and albumin dynamics prior and regardless of the development of diabetes." (PMID 32850773, 2020). "The purpose of this review was to scope the evidence of current products on the market for diabetes, and not systematically review all supplements related to glycemic control and insulin sensitivity." (PMID 32341338, 2020). "Diabetes mellitus (DM) is an endocrinological disorder that is due to either the pancreas not producing enough insulin, or the body does not respond appropriately to insulin." (PMID 33255227, 2020). "In a recent study, we specifically investigated the contributions of ghrelin to the CRR to insulin-induced hypoglycemia using mice without diabetes." (PMID 33042003, 2020).
diabetes (continued). "Adipsin showed a significant (p < 0.01) association with a few adipocytokines but not with diabetes measures (body weight, BMI, glucose, and insulin)." (PMID 33233515, 2020). "In our study patients with diabetes who required insulin were not higher in 8 mg group (5.46%) compared to 4 mg group (7.43%)." (PMID 33047085, 2020). "A multicenter, randomized clinical trial compared the effects of transient intensive insulin therapy—continuous subcutaneous insulin infusion (CSII) or multiple daily injections (MDI)—versus oral antidiabetic agents on beta-cell function and diabetes remission." (PMID 32489427, 2020). "Recently, our research group established a novel, non-obese mouse strain with spontaneous diabetes, called the insulin hyposecretion (ihs) mouse." (PMID 32502168, 2020). "Last, we did not perform lab tests commonly used in screening for pre-diabetes (i.e. insulin level, oral glucose tolerance test)." (PMID 32226033, 2020). "Diabetes mellitus (DM) is a chronic, noncommunicable disease with high morbidity and mortality due to chronic deterioration of insulin-producing cells." (PMID 33217903, 2020). "The suggestion is also supported by significantly higher insulin concentration in HMB-treated rats with diabetes, unless the results were not corrected for multiple testing." (PMID 33114049, 2020). "Studies about bone repair and type 2 diabetes show that long bones suffer with the impact of diabetes, especially type 1 where there is a lack of insulin which has a role as an anabolic substance affecting bone." (PMID 33339217, 2020). "Insulin use in patients without diabetes was associated with worse clinical outcomes compared to patients (both with and without diabetes) who did not receive insulin." (PMID 33118731, 2020). "Diabetes mellitus is a condition in which the body has high blood sugar levels (hyperglycemia) due to a lack of insulin hormones, impaired secretion of insulin, or both." (PMID 32235629, 2020). "Insulin is one of the main treatments for diabetes, but long-term injections can lead to a lack of patients’ compliance and pain." (PMID 33092194, 2020). "Diabetes mellitus is a metabolic derangement either due to lack of insulin or resistance to insulin and its resulting hyperglycemia." (PMID 33457130, 2020). "Glycated hemoglobin value displayed mild increasing tendency during gestation, which indicates stable insulin resistance in patients irrespective of the type of diabetes mellitus." (PMID 33184417, 2020). "There are two principal forms of diabetes: Type 1 diabetes (formerly known as insulin-dependent) in which the pancreas fails to produce insulin which is essential for survival." (PMID 33294218, 2020). "In alloxan-induced diabetes in rats without infection, hyperglycemia and absence of insulin did not change, for example, autophagosome LC3 levels in bronchoalveolar lavage fluid." (PMID 33312173, 2020). "Insulin was not required initially, but rapidly progressed to the requirement of insulin within 1 year of diabetes diagnosis." (PMID 32982980, 2020). "Chromium improves the glucose/insulin levels in subjects with hypoglycemia, hyperglycemia, diabetes and hyperlipidemia, with no detectable effects on control subjects." (PMID 32585827, 2020). "Ethologically, DM is categorized as type 1 diabetes (T1D), largely resulting from autoimmune destruction of insulin-producing β-cells and defect in insulin production, and type 2 Diabetes (T2D) which may be due to insulin resistance in peripheral tissues such as muscle and adipose." (PMID 32695298, 2020). "The principle of subclassifying diabetes using genetics and applying this knowledge to guide therapeutic decision making has proof of principle in the monogenic form of diabetes called MODY, which is characterised by defects in the development of the pancreatic islet cells and insulin secretion." (PMID 32840675, 2020).
diabetes (continued). "This advocates that the effect of exercise primarily benefits patients with shorter diabetes duration not yet in need of exogenous administered insulin." (PMID 32903679, 2020). "Acadsb has down‐regulated expression not reversed by insulin treatment and Aldh3a has up‐regulated expression with diabetes, not reversed by insulin treatment." (PMID 33200530, 2020). "At present, the drugs widely applied in clinical treatment of diabetes mellitus mainly include insulin, insulin analogs, non-insulin oral hypoglycemic drugs and genetic drugs." (PMID 32850735, 2020). "The results of the Survey for People who do not take Insulin (SPI), which was designed to identify the reasons why patients with diabetes refuse insulin treatment, showed a negative attitude towards insulin administration in subjects with poor self‐efficacy." (PMID 32257276, 2020). "The unadjusted mortality rate for patients without diabetes receiving postoperative insulin was higher than that of all patients not receiving insulin (odds ratio [OR]=2.03; 95% confidence interval [CI] 1.15-3.57; P=0.014)." (PMID 33118731, 2020). "Overall, patients without diabetes receiving postoperative insulin appear to have higher mortality and more complications compared with patients not receiving insulin." (PMID 33118731, 2020). "To test this hypothesis, we examined the time course of changes in insulin+ islets and pancreatic nerves in mice with STZ-induced diabetes, as well as in age- and sex-matched C57BL/6 mice." (PMID 33036983, 2020). "Since the time–action profile of rapid-acting insulin better mimics endogenous insulin compared with regular human insulin (RHI), it has been assumed that rapid-acting insulin should be used in pumps for treating patients with diabetes." (PMID 31692373, 2020). "Interestingly, treatment with DiaPep277 in pre-clinical animal models of diabetes also modified the TH1 responses to other β-cell and diabetes-related autoantigens, such as insulin and GAD." (PMID 33584694, 2020). "The children with type 1 diabetes mellitus who do not have regular access to insulin are likely to have earlier onset of long term renal complications showing as microalbuminuria." (PMID 32874425, 2020). "In a study that looked at the levels of glucose transporter expression in placental tissue from mothers with diabetes mellitus, they found there was a significant increase in the expression of GLUT-9 in diabetic mothers controlled by insulin, as well as pregestational diabetes." (PMID 32075680, 2020). "The insulin-mediated IRS-PI3K-AKT signaling pathway is therefore a key pathway affecting the metabolic effects of insulin and is usually dysregulated in people with diabetes." (PMID 33568996, 2020). "None of the co-morbid pathologies of diabetes (reduced body weight, reduced glucose tolerance, and reduced insulin sensitivity) were present in the KMO KO mice." (PMID 32151061, 2020). "A similar finding was reported in a study of subjects with hypertension and diabetes, in which consumption of 25 g of dark chocolate for 8 weeks did not improve insulin, fasting glucose, or HbA1c levels." (PMID 33266002, 2020). "During endurance exercise in individuals without diabetes, insulin secretion decreases via increased sympathoadrenal drive, with the magnitude of decline closely linked to activity intensity and duration." (PMID 32533229, 2020). "Patients not receiving insulin (12.76% of whom had diabetes) had higher rates of smoking and chronic lung disease but presented with a generally lower New York Heart Association class." (PMID 33118731, 2020). "After 20 years of diabetes, nearly all patients with type I diabetes, 80% of patients with type 2 diabetes requiring insulin treatment and 50% of those not requiring insulin treatment exhibit some degree of DR3." (PMID 32051471, 2020). "Insulin use, particularly continuous insulin infusion use, is common in both patients with and without diabetes following CABG." (PMID 33118731, 2020).